TTF1 (transcription termination factor 1)
Diseases named in the same sentence as TTF1 in open-access papers (continued):
Sharing a sentence is not in itself a finding about the gene and the disease.
tumor (continued). "However, all the tumor cells (both the surface-lining and polygonal cells) were positive for thyroid transcription factor 1 (TTF-1), which is expressed not only in thyroid epithelial cells but also in type II pneumocytes and Clara cells, and epithelial membrane antigen." (PMID 24944657, 2014). "The tumor cells include typical superficial lining cells and underlying round cells, which might origin from the pulmonary epithelial cells, characterized by the positive staining of epithelial markers, such as EMA and TTF-1." (PMID 23587094, 2013). "Interestingly, we found that TTF-1 functions as a tumor-suppressor during EMT induction." (PMID 22111550, 2012). "Additionally, TTF-1 is reported to be expressed inversely in relation to tumour differentiation." (PMID 21811254, 2011). "Immunohistochemically, the tumor showed strong positivity for CK19, CK7, and CD34 in ductular–trabecular structures, as well as glypican-3 and TTF-1 in solid components." (PMID 40843884, 2025). "Although TTF-1 or its gene NKX2-1 functions both as a lineage oncogene and a tumor suppressor, its role in the TIME has been less studied." (PMID 40824335, 2025). "Histopathological confirmation was obtained via liver biopsy or surgical specimen, with immunohistochemistry performed to assess tumor differentiation using markers such as CK7, CK19, CK20, CK AE1/AE3, glypican-3, TTF-1, and CD34." (PMID 40843884, 2025). "Immunohistochemical (IHC) stains showed tumor cells positive for CK7, TTF-1, and napsin A, with patchy, weak nuclear reactivity for CDX2." (PMID 40524907, 2025). "While TTF1, CK7, and NAPSA are routinely utilized for tumor origin identification and classification, LPL offers a novel perspective by reflecting changes in tumor metabolism and the tumor microenvironment." (PMID 40427755, 2025). "Immunohistochemically, the tumor cells showed positive expression of CK7, TTF-1, napsin A, and Ki-67 (approximately 35% in hot spots), and were negative for CK5/6 and P40." (PMID 40746613, 2025). "Immunophenotyping found tumor cells that were CK (+), CD56 (+), Syn (+), EMA (+), β-catenin (membrane +), LCA (−), CD99 (−), S100 (−), HMB-45 (−), SOX-10 (−), TTF-1 (−), CDX-2 (−), and CD34 (−), along with a Ki-67 proliferation index of 60–70%." (PMID 41245381, 2025). "The two cases were diagnosed as invasive lung adenocarcinoma, and immunohistochemical staining showed that all tumor cells expressed CK7, Napsin A, TTF-1, and PD-L1." (PMID 41383499, 2025). "In this case, the immunohistochemical results of the specimen after surgical resection showed the tumor cells positively expressed CK, Brg1, and INI-1, while negatively expressed TTF-1, Napsin A, p40, p63, CK5/6, and others." (PMID 40969808, 2025). "IF staining revealed that all organoid lines were positive for TTF-1 and CK7 expression, consistent with their parental tumor counterparts, thereby indicating their LUAD identity." (PMID 40275403, 2025). "While TTF‐1‐positive TPPIs including GCT, PTC, and SCO have a distinctive methylation profile, the tumor methylation profile confidence score for PTC was 0.3 and therefore not indicative of pituicyte origin." (PMID 39350562, 2025). "Immunohistochemical results showed that TTF-1 and EMA were positive in epithelial and stromal cells of almost all tumor tissues." (PMID 40061895, 2025). "NKX2-1 (NK2 Homeobox 1; TTF-1) is a lineage transcription factor frequently amplified or overexpressed in LUAD; such gain sustains epithelial identity and tumor fitness." (PMID 41154602, 2025). "Immunostains performed on the tumor cells within the cell block were positive for cytokeratin 7 (CK7), TTF-1, napsin-A, and weak patchy for paired-box gene 8 (PAX8)." (PMID 39318937, 2024).
tumor (continued). "Evidence of TTF-1 expression in non-pulmonary small cell cancers, such as aggressive small cell prostate cancer, supports its association with neuroendocrine differentiation and aggressive tumor behavior rather than characteristics of terminal respiratory unit cells." (PMID 39392394, 2024). "The tumor was positive for cytokeratin AE1/AE3, carcinoembryonic antigen, synaptophysin, chromogranin, thyroid transcription factor 1 (TTF-1), S-100, and calcitonin." (PMID 39553134, 2024). "The immunohistochemical results showed that tumor cells expressed cytokeratin (CK), CK5/6, CK7, P63, and thyroid transcription factor 1 (TTF1) positively." (PMID 39081690, 2024). "Immunohistochemical analysis of tumor cells revealed the following results: AE1/AE3(+), TTF-1(–), p40(–), chromogranin A(–), synaptophysin(–), CD56(–), INSM1(–)." (PMID 39463789, 2024). "Immunohistochemistry showed that tumor cells expressed neuroendocrine markers (CD56, CgA, or Syn), TTF-1, and CK." (PMID 37608278, 2023). "Ancillary testing for some specific tumours (e.g. SMARCA4-deficient (lung) adenocarcinoma–which is typically TTF-1 negative) is not available or not done routinely on brain metastatic specimens (e.g. lung biomarker panel); this limits the ability of the pathologist to classify some tumours." (PMID 37943775, 2023). "We next compared tumours from the SCC and ADC subtypes, as determined by keratin 5 (Krt5), thyroid transcription factor 1 (Ttf-1/Nkx2-1) and Usp28 staining, in KPL mice." (PMID 37202505, 2023). "Tumor cells in the epithelial and mesenchymal regions were negative for DOG-1, CD34, S-100, SOX-10, STAT 6, SMA, C-Kit, Calretinin, Syn, CgA, TTF-1, ER, and PR." (PMID 37658451, 2023). "To confirm these results, we performed immunohistochemistry (IHC) analysis of the tumor samples of A549‐WT and A549‐SUCLG2‐KO using anti‐Ki67, anti‐TTF1, and anti‐SUCLG2 antibodies." (PMID 37904651, 2023). "For immunostain, the tumor cells were weakly positive for SMA and strongly positive for Vimentin, but negative for other markers such as AE1/AE3, CK7, CK18, CK19, CK5/6, p63, TTF-1, EMA, CD34, desmin and so on." (PMID 36759857, 2023). "In such instances, macrophage markers, such as CD68 or CD163, and markers for follicular cell lineage, TTF-1, PAX8, and thyroglobulin, can help to confirm the presence of tumor cells within a vessel lumen." (PMID 37324272, 2023). "Immunohistochemically, thyroid transcription factor-1 (TTF-1, +), synapsin (Syn, −), epithelial membrane antigen, (EMA, +), and carcinoembryonic antigen (CEA, −) were shown in both tumor cell types." (PMID 37665739, 2023). "We retrospectively assessed the efficacy of TTF-1, CK7, P63, P40, and Napsin A, IHC markers in differentiating and sub-classifying ADC, NSCLC, and SCC on TCBs to determine the accuracy of the tumour markers." (PMID 36712764, 2022). "Although three recent papers reported three unusual cases of NSCLC with co-expression of TTF1 (NKX2-1) and p40 (TP63) in the same cells by IHC staining, they failed to observe the molecular heterogeneity present in an individual tumor." (PMID 35962452, 2022). "The tumor showed the expression of cytokeratins, such as CK8-18 and AE1/AE3, and typical CD99 expression, whereas immunostaining for thyroglobulin, TTF1, PAX8, calcitonin, CK20, SOX10, ERG, SMA, and NUT was negative." (PMID 36129618, 2022). "Multiplex fluorescent IHC staining of TTF1 and UCHL1 on tumor tissues from P11 also verified the coexpression of these two markers in a high proportion of tumor cells." (PMID 35962452, 2022).
tumor (continued). "The level of TTF-1 in the nucleolus is changed upon DNA damage and oncogenic stress, when the tumour suppressor p19/14 ARF is induced and inhibits the nucleolar localisation of TTF-1." (PMID 34202617, 2021). "The immunohistochemistry of the tumor showed AE1/AE3 (+), Ki-67 (2% +), CK7 (+), Vimentin (+), CK19 (+), α1-ACT (+), AB-PAS (+), S-100 (−), TTF-1 (−)." (PMID 34663287, 2021). "TTF1 and GATA3 regularly show an inverse staining pattern and GATA3 is less expressed in more solid/spindled and sarcomatoid regions of the tumor." (PMID 33670088, 2021). "Surprisingly, 77.8% (14/18) cases showed positive staining of the nuclei of tumor cells for TTF1 using the EP229 clone in embryonal, GFAP-negative tumor components only." (PMID 33876327, 2021). "Tumor samples in the present study had been stained for markers including NUT, P63, P40, TTF-1, keratin, CK7, Syn, CD56, CgA, CD34, CD117, EGFR, and Ki-67." (PMID 32149149, 2020). "Exemplarily, we found that TTF-1 was highly expressed in many LUAD and was a useful protein to differentiate LUAD from every other tumor type both in fresh frozen and in FFPE tissue, consistent with its wide use in diagnostics." (PMID 32601356, 2020). "These tumours resemble the marker expression of the primary cell line and maintained SCC lineage identity (TTF1−/KRT5+/∆Np63+)." (PMID 32128997, 2020). "When compared with a metastatic nephroblastoma (Wilms tumor), positivity for thyroglobulin and TTF-1 and only cytoplasmic and very limited positivity for WT1 distinguish this tumor from metastatic Wilms tumor." (PMID 32632840, 2020). "According to postoperative pathological and immunohistochemical markers, there were two epithelial cell groups in the tumor, one of which expressed CKs AE1/AE3, hepatocyte, TTF1, AFP, and CD10 and another expressing CK7 and CK19." (PMID 32967689, 2020). "In LADC cells, TTF‐1 interacts with the Smad family TFs downstream of TGF‐β signaling to inhibit EMT, providing a mechanism of tumor suppressor function of TTF‐1." (PMID 31782890, 2020). "Reduction of lymph nodes metastases and serum tumour markers have also been reported in a BM-CUP (positive for Napsin A, TTF-1, and EGFR exon 19 deletion) treated with the EGFR-TKI gefitinib." (PMID 33198246, 2020). "In a murine LADC model, TTF‐1 physically binds and interacts with FOXA, providing a direct connection between transcriptional lung differentiation programs and tumor initiation." (PMID 31782890, 2020). "Immunohistochemically, the tumor cells were positive for neuroendocrine markers (chromogranin A, synaptophysin, CD56) and thyroid transcription factor-1 (TTF-1)." (PMID 31511024, 2019). "Immunohistochemically, the tumor cells were positive for chromogranin A, synaptophysin, CD56, and TTF-1 and the Ki-67 index was 27%." (PMID 31511024, 2019). "Addition of CK5 with cutoff 10% positive tumor cells for a positive staining identified an additional 8 SqCC cases (and one additional AC with solid growth was positive for CK5 but also for both TTF-1 clones in >50% of the cells)." (PMID 30718697, 2019). "Immunohistochemical analyses confirmed the tumor as thyroid-derived, as the cells were uniformly positive for cytokeratin MNF116, PAX8 and TTF1." (PMID 31699114, 2019). "It was observed that the treatment of miR-200b significantly abrogated the AP-2α/MAPK7/TGF-β expression, leading to increased expression of E-cadherin and TTF-1 and decreased expression of fibronectin and α-SMA in tumor tissues." (PMID 29084594, 2017). "Immunohistochemically, tumor cells were positive for cytokeratin (CK)-AE1/3, CK7, TTF-1, CEA, calcitonin, synaptophysin, and chromogranin A, but negative for CK20, Napsin A, Pax8, and p40." (PMID 29237502, 2017).
tumor (continued). "Tumor cells in TRU-type adenocarcinoma had a dome-shaped or protruding cytoplasm and showed strong but diffuse expression of TTF-1." (PMID 27575252, 2016). "The immunohistochemical profile of the tumor (CK7 and TTF1 positive) suggested a primary origin from the lung." (PMID 26689995, 2016). "The tumor was immunonegative for GFAP and Syn, whilst it was immunopositive for vimentin, EMA, S-100 and TTF-1." (PMID 25777996, 2015). "The intraoperative assessment revealed that the tumor had a rich blood supply and the SCO tumors were immunopositive for vimentin, S-100, EMA and TTF-1." (PMID 25777996, 2015). "Based on the tumor node metastasis (TNM) staging system, this sarcomatoid carcinoma, favor lung origin (TTF-1 positive), with bone, bone marrow, liver, duodenum, and colon metastases, was classified as stage IVB (pTxN2bM1b)." (PMID 25947890, 2015). "The immunostaining patterns of TTF-1, Napsin A, CK7, P63 and CK5/6 were correlated with the histological diagnosis of the tumor." (PMID 25977750, 2015). "The tumor was immunonegative for GFAP, creatine kinase, Syn and B-cell lymphoma 2; however, it was immunopositive for vimentin, EMA, S-100 and TTF-1." (PMID 25777996, 2015). "The results of the present study proved that the cuboidal tumor cells expressed CKpan, SPB, TTF-1 and EMA, and polygonal cell tumor cells expressed TTF-1 and EMA, which supports the SHL primitive alveolar epithelial cell origin." (PMID 25130377, 2014). "In all 18 cases of SHL, TTF-1 and EMA were expressed in both polygonal tumor cells and cuboidal tumor cells(18/18, 100%)." (PMID 25130377, 2014). "The immunohistochemical profile of the current tumor is comparable to previously reported TLFCK cases (AE1/AE3+, CK7+, PAX-2+, PAX-8+, vimentin+, EMA+, TTF-1−, TG−, CD56−, WT-1−, CD10−, and CEA−)." (PMID 25133003, 2014). "Immunohistochemical (IHC) staining test results showed that the tumor cells were positive for pancytokeratin (AE1/AE3), cytokeratin 7 (CK-7), thyroid transcription factor 1 (TTF-1) and carcinoembryonic antigen (CEA)." (PMID 24330633, 2013). "The tumor tissue from our patient showed monotonous clear cells arranged in a glandular pattern, positive immunoreaction results for AE1/AE3, CK-7, TTF-1, CEA, Ki-67, and positive PAS staining for the existence of glycogen in clear cell cytoplasm." (PMID 24330633, 2013). "Thus, TTF-1 may exert a tumor-suppressive effect through antagonizing the effect of TGF-β." (PMID 22111550, 2012). "Most of the tumor cells were found to have a positive reaction for pan-cytokeratin, CK7, TTF1, chromogranin A and synaptophysin." (PMID 23119202, 2012). "Immunofluorescence analysis, real time RT-PCR and Western blot studies revealed that TTF-1 as well as the major Wnt pathway components are co-expressed in TPC-1 cells and human PTC tumours." (PMID 21814573, 2011). "Immunohistochemically the tumor was positive to synaptophysin, neuron specific enolase (NSE), CD56 and TTF1." (PMID 21087512, 2010). "The tumor cells were positive for neuroendocrine markers chromogranin, and synaptophysin as well as CD56 and Thyroid Transcription Factor-1 (TTF-1)." (PMID 20807418, 2010). "The tumor cells were positive for CK7 and TTF-1, and weakly positive for p63 suggesting a diagnosis of adenocarcinoma." (PMID 20376244, 2009). "Spatial transcriptomic profiling of ASC was integrated with TTF-1 and p40 IHC to detect tumor populations lacking these markers." (PMID 41571939, 2026). "The tumour was negative for TTF‐1, napsin A, CK5/6, and p40 staining by IHC and was diagnosed as NOS (not otherwise specified)." (PMID 39950095, 2025). "There is substantial evidence demonstrating the prognostic and predictive value of TTF-1 in LUAD, with its expression associated with favorable prognosis, independent of tumor stage." (PMID 39630375, 2025).
tumor (continued). "Immunohistochemistry demonstrated tumor positivity for vimentin, epithelial membrane antigen (EMA), progesterone receptor (PgR), and thyroid transcription factor-1 (TTF-1) and negativity for cytokeratin and B-cell lymphoma-2 (Bcl-2), with a Ki-67 proliferation index of <1%." (PMID 40265140, 2025). "Immunohistochemically, the absence of a positive reaction for thyroglobulin and TTF-1 excluded the secondary origin of the tumor from the thyroid." (PMID 40361930, 2025). "One of the adenocarcinomas expressed TTF1, but the other tumor was negative, raising concerns for differential diagnosis." (PMID 40407482, 2025). "The correlation between TTF-1 positivity and absence of necrosis potentially reflects a less aggressive tumor biology also given the favorable trend in survival." (PMID 40869558, 2025). "Immunostaining of the tumor cells was positive for MNF-116 and patchily positive for p40, while negative for leukocyte common antigen (LCA (CD45)), S100, smooth muscle actin (SMA), thyroid transcription factor 1 (TTF-1), and synaptophysin." (PMID 41625888, 2025). "Immunohistochemical studies confirmed the diagnosis, with tumor cells positive for pancytokeratin, TTF1, synaptophysin, and INSM1, and negative for Napsin-A, p40, WT1, calretinin, and chromogranin." (PMID 40403473, 2025). "This is in line with some previous studies, which showed that both TTF-1 and Napsin A are not exclusively expressed in adenocarcinomas of the lung and thyroid gland, but also in other tumor entities (albeit to a lower extent)." (PMID 40564811, 2025). "The tumor cells showed strong nuclear expression for GATA3 but no staining for TTF-1, CDX2, and PAX8, inferring primary breast origin." (PMID 40909459, 2025). "At immunocytochemistry, the tumor cells were positive for Syn, focally positive for galectin, TTF1, CDX2, thyroglobulin, and negative for Ct and CgA." (PMID 40542625, 2025). "We acknowledge that immunohistochemical markers such as SMA, desmin, caldesmon, TTF-1, and Napsin A are not entirely specific to their respective tumor types." (PMID 40666089, 2025). "Immunohistochemical results showed that the tumor cells positively expressed epithelial membrane antigen (EMA), thyroid transcription factor 1 (TTF1), NapsinA (epithelial cells) and cytokeratin 7 (epithelial cells), while negatively expressed chromogranin A (CgA) and synaptophysin (Syn)." (PMID 40061895, 2025). "Immunohistochemistry showed that the tumor cells were positive for TTF1 and Napsin A and negative for p40 and CK5/6." (PMID 40507353, 2025). "TTF-1 and ASCL1 cooperatively promote neuroendocrine differentiation and tumor growth." (PMID 40437627, 2025). "Immunohistochemical staining revealed that the tumor was negative for thyroid transcription factor-1 (TTF1), Napsin A. The tumor was focally positive for CK5/6, but not for p40." (PMID 40507353, 2025). "The immunohistochemistry profile was variable according to the primary tumor, CgA, Syn, and keratins were generally positive, while Tg, Ct, and TTF1 were negative." (PMID 40542625, 2025). "Recently, in a bicentric cohort of patients with resected LUAD, TTF-1 positivity was associated with longer disease-free survival (DFS), irrespective of tumor grade, as shown by a Bayesian network analysis." (PMID 39630375, 2025). "For example, GATA3 in combination with ER, mammaglobin, and PR supports the breast origin; TTF1 and Napsin A suggest a pulmonary source; CK20 and CDX2 indicate a neoplasia of the lower gastrointestinal tract, CD10, alongside PAX8, typically points toward renal origins, and many more." (PMID 40407482, 2025). "TTF-1 immunostaining, being widely available, may serve as a surrogate predictor of ICI response and a more inflamed TIME, especially when tumor cell PD-L1 is low." (PMID 40824335, 2025).